INS (insulin)
Diseases named in the same sentence as INS in open-access papers (continued):
Sharing a sentence is not in itself a finding about the gene and the disease.
Obesity (continued). "The majority of studies evaluating whether Metinflex is associated with obesity, have used a cross-sectional design limiting our comprehension about whether Metinflex develops with fat mass increase leading to insulin resistance." (PMID 34209545, 2021). "Although exact mechanisms are not fully understood yet, there are numerous studies that underline mutual impact of obesity and insulin resistance in increased inflammation, suggesting probabilistic initiating or modulating influence of these states on PCOS pathogenesis." (PMID 33917519, 2021). "SCFA-producing bacteria (Lachnoclostridium, Ruminococcus_1, Alloprevotella, and norank_f_Muribaculaceae) can not only cause lipolysis and fatty acid oxidation, improve insulin sensitivity, and alleviate host obesity, but also inhibit liver cholesterol synthesis." (PMID 34579118, 2021). "The pleiotropic effects of TGF-β/Smad3 signaling on cell metabolism and energy homeostasis plays an important part in the progression of obesity-linked diabetes; these include adipocyte differentiation, adipose browning, inflammation and regulation of insulin signaling amongst others." (PMID 33897620, 2021). "As mTORC1 integrates not only signals arising from insulin but also nutrients, it has been suggested that nutrient signals such as amino acids could be excessive in obesity and replace the deficient insulin signal, thus worsening IR." (PMID 34298896, 2021). "Lower insulin in circulation also prevents leptin-deficient Lep ob/ob mice from developing obesity." (PMID 34032632, 2021). "An abundance of Akkermansia muciniphila, has been linked to a healthy metabolic profile, with greater improvement in obesity-associated metabolic parameters (plasma triglycerides, body fat distribution, and insulin tolerance) for individuals with obesity following dietary intervention." (PMID 34168615, 2021). "Thus, meal- and obesity-associated increases in insulin, acting via ghrelin cell–expressed IRs, represent a major, direct negative modulator of ghrelin secretion in vivo, as opposed to ingested or metabolized macronutrients." (PMID 34473648, 2021). "Obesity induces a state of chronic, low-grade inflammation in fat that is accompanied by the local secretion of cytokines and chemokines, causing attenuation of insulin action." (PMID 34685582, 2021). "Likewise, Ide polymorphisms have been associated with obesity, metabolic syndrome, polycystic ovary syndrome, and decreased hepatic insulin clearance." (PMID 33668109, 2021). "In addition, obesity is associated with a reduction in the cognitive-enhancing effects of intranasal insulin in humans and impairments in hippocampal glutamatergic plasticity." (PMID 33514676, 2021). "Consequently, IR is more strongly associated with a metabolically unhealthy status than is obesity, leading to the use of insulin sensitivity indices." (PMID 34742239, 2021). "However, the obesity-associated rise in serum insulin concentrations was reduced in HFD-fed animals treated with len-βFaar." (PMID 34183666, 2021). "Thus, one of the possible effective methods of preventing or reducing the risk of the CHO-insulin model of obesity is to reduce the CHO proportion of the diet." (PMID 33922998, 2021). "Furthermore, previous studies have shown the critical roles of key transcription factors or miRNA in regulating the genetic network associated with β cell insulin secretion and proliferation in the context of obesity." (PMID 34572101, 2021). "Furthermore, these inflammatory effects were suppressed, after weight loss, in the subcutaneous fat of patients with obesity and T2D, with consequent improvement in insulin sensitivity." (PMID 33809891, 2021). "The results suggest that improvements in CEC, through improvement in adipose tissue health in terms of adipokine secretion and insulin sensitivity could be an important pathway in modulating obesity-related CVD risk." (PMID 33865458, 2021).
Obesity (continued). "Therefore, the aim of the present study was to investigate its effects on obesity, insulin sensitivity, the gut microbiota and the underlying molecular mechanisms in HFD-induced hyperglycaemia." (PMID 35052549, 2021). "Furthermore, regulating FGF15/19 affects carbohydrate and lipid metabolism, including TG concentrations, insulin sensitivity, weight loss, and obesity-associated hyperlipidemia." (PMID 35010970, 2021). "Myriocin (a de novo ceramide synthesis inhibitor) treated mice exhibited a reduced ceramide content in the liver resulting in improved hepatic insulin signaling, thereby proposing ceramide synthesis as a novel and promising target for the treatment of obesity-associated insulin resistance." (PMID 34385976, 2021). "Furthermore, both GPR10 knockout mice and PrRP-deficient mice developed late-onset obesity and exhibited a significant decrease in energy expenditure compared to wild-type mice as well as altered insulin sensitivity and lipid homeostasis." (PMID 34867411, 2021). "This protection against obesity might be due to reduced insulin production and secretion related to the rs7903146 T allele once insulin stimulates the increased glucose uptake in adipocytes." (PMID 33996288, 2021). "If some of these proteins fail in their function, some tissues may become insulin resistant, which is associated with metabolic pathologies like obesity." (PMID 34829598, 2021). "Besides, metabolic changes associated with obesity such as insulin and leptin resistance negatively impact immune cell function." (PMID 33390183, 2021). "In addition, p300 is important for the maintenance of β-cell function, promotes glucose-induced insulin secretion and is associated with the disruption of insulin signaling in obesity." (PMID 34483940, 2021). "Studies conducted on mice indicate that knockout of CYP2E1 may increase the body’s sensitivity to insulin and protect it against glucose intolerance and obesity caused by a HFD." (PMID 34576213, 2021). "Metabolic resistance has also been indicated to be shared between insulin and ASP, where the increase in insulin levels might be caused by obesity." (PMID 34829865, 2021). "If PPG concentrations exceed the capacity of insulin to clear glucose into the tissues through insulin dependent glucose transporters, this may lead to lipogenesis, which will ultimately contribute to weight gain and increased risk for obesity." (PMID 34679949, 2021). "In addition, though insulin sensitivity was impaired, iron overload protected the liver from obesity-associated pathological conditions like hepatic steatosis." (PMID 34441564, 2021). "The modified insulin signaling axis, the release of adipokines, and lastly, low-grade chronic inflammation are plausible molecular mechanisms for the association between obesity and hematological neoplasms." (PMID 33531904, 2021). "For these obesity‐associated diseases, carbohydrate restriction may be the optimal modality for elevating ketone bodies while decreasing insulin and blood glucose concentration." (PMID 34631141, 2021). "validated that the obesity-driven elevated insulin could upregulate mitochondrial glucose oxidation in obesity-associated tumor cell lines (BC, colon cancer, and prostate cancer cells) correlated with a dose-dependent increase in cell division." (PMID 34350120, 2021). "Increased intakes of HLD induced obesity and increase the level of insulin are directly linked with higher insulin-like growth factor-I in circulation which is a critical factor for the development of different cancers, including prostate cancer via modulation of IGF-I receptor (IGF-IR) signaling." (PMID 34026558, 2021). "Moreover, some studies showed that testosterone (T) has immune-downregulating properties, associated with an improvement of insulin and leptin sensitivity and other parameters of obesity and MetS." (PMID 33557413, 2021). "AAAs are strongly associated with obesity-related impaired insulin sensitivity patients." (PMID 34209599, 2021).
Obesity (continued). "Moreover, in obese mice, reducing the circulating insulin levels via genetic manipulation led to significant body weight loss within 5 weeks and reversed the existing obesity." (PMID 32029228, 2020). "A relationship between insulin sensitivity and magnesium levels and an inadequate intake due to a poor quality of the diet were reported as key factors contributing to the association between obesity and low magnesium levels." (PMID 31947724, 2020). "Consistent with these mechanistic findings, mouse studies have shown that supplementation with acetate, propionate, butyrate, or some mixture of these can protect against weight gain, improve insulin sensitivity, and reduce obesity-associated inflammation (24, –, 29)." (PMID 32788375, 2020). "Thus, it has now been proposed that obesity-associated FGF21 is increased as a compensatory mechanism to preserve insulin sensitivity." (PMID 32158768, 2020). "Early Western diet induced neuronal density and phenotype changes in PINS that might be involved in the pancreas insulin secretion dysfunctions associated with obesity." (PMID 31922022, 2020). "Following the onset of CHF, obesity per se is associated with higher skeletal muscle mass and tissue ATP production, lower mitochondrial ROS production, improved redox state, cytokine profile and insulin signaling." (PMID 33158222, 2020). "High levels of leptin and insulin in the blood are associated with obesity." (PMID 33046129, 2020). "Similarly, the Keap1-hypo allele (Nrf2 activation) mice were partially protected from obesity, had lower fasting glucose and insulin levels, and developed less liver steatosis." (PMID 32443555, 2020). "Increasing evidence supports that metabolic inflammation is a consequence of obesity and it may play, in turn, a causative role in blunting insulin sensitivity and disrupting metabolic/energy homeostasis." (PMID 32188105, 2020). "At the point when established hazard variables like smoking are superimposed on the insulin resistant state of obesity they may additionally increase less conventional risk factors intensifying the existing cardiovascular issues." (PMID 32432000, 2020). "Obesity and insulin dysregulation (ID) predispose horses to laminitis." (PMID 32557899, 2020). "According to clinical observations, weight loss-induced improvements in glycemia are most likely to occur early in the natural history of T2DM, when obesity-associated IR has caused reversible ß-cell dysfunction, but insulin secretory capacity remains relatively preserved." (PMID 33381036, 2020). "We therefore aimed to test the hypothesis that the FA compositions of RBC-TPL and depot-specific SAT are associated with central body fat distribution and insulin sensitivity in black South African women with obesity." (PMID 32486525, 2020). "To the best of our knowledge, for the first time, we demonstrated that obesity-related circulating exosomes can impair insulin signaling pathways and associated components, as well as increase intracellular TG content, and decrease the secretion of FGF21 in the hepatocytes." (PMID 32322309, 2020). "In the study of obesity, adipose tissue is more useful than just its basic physiological functions (storage and release of fat); adipose tissue plays an important role in insulin sensitivity and is the site of the synthesis of many hormones and other signaling molecules associated with obesity." (PMID 33203044, 2020). "Not only is obesity remarkably common (13% of the adult population worldwide is obese and 39% overweight) and very challenging to treat, but it is also tightly linked to insulin resistance and vascular dysfunction." (PMID 31991894, 2020). "Estimation of appendicular LST mass in obesity is of interest because it is significantly associated with insulin levels in overweight or obese women, independently of age, body size or fat mass 55 and increasing skeletal muscle is associated with decreased insulin sensitivity." (PMID 32308541, 2020).
Obesity (continued). "The relationship between circulating vaspin levels and insulin sensitivity parameters indicates the important role of this molecule in the pathogenesis of metabolic disorders associated with obesity, although mechanism of vaspin action remains under investigation." (PMID 32917052, 2020). "Insulin sensitizers like PPARγ antagonists increase obesity and fracture risk." (PMID 32204420, 2020). "Of these, calcium signaling is crucial for insulin secretion in pancreatic β-cells, while phosphatidylinositol signaling is known to play an important role in an insulin-stimulated glucose metabolism pathway associated with obesity and T2D." (PMID 32093692, 2020). "Obesity is associated with a reduced effect of insulin on glucose cell uptake, and it has been described that it also impairs its vasodilating arterial effect, which may contribute to the development of metabolic syndrome." (PMID 32093229, 2020). "This is the first time that normal genetic variation in these genes has been related to bone mass, and moreover, of great potential interest in cardiovascular risk assessment, the first time that genetic variants in CARM1 gene have been correlated with obesity and fasting insulin levels." (PMID 33004909, 2020). "The modulation of T cell differentiation, promoting a shift toward a Th2-type anti-inflammatory response may also contribute to the favorable influence of insulin on chronic inflammation associated with obesity and T2D." (PMID 32397353, 2020). "Because of the vast number of youths having or are at risk of obesity and because IR may occur as part of the physiological changes in puberty, early detection of impaired insulin sensitivity in adolescents is pivotal to designing targeted preventive actions." (PMID 32873820, 2020). "The interaction between smoking and obesity on the risk of insulin-requiring GDM was tested." (PMID 32807828, 2020). "Overweight and obesity are generally considered to be important risk factors for adverse maternal and neonatal outcomes due to the effects of oxidative stress, proinflammatory status, alterations in placental function, and insulin insensitivity." (PMID 32074959, 2020). "Therefore, in the present study, we used an insulin-deficient diabetic animal model, which also allows us to differentiate the complications resulting from the hyperglycemic state vs. obesity." (PMID 32903422, 2020). "Moreover, mRNA expression of SEMA3C in adipose tissue was associated with insulin sensitivity, suggesting pathophysiological roles in human obesity and metabolic deterioration." (PMID 32561824, 2020). "Also, hyperinsulinemia has been suggested to be one of the major factors causing obesity-associated hypertension, as increased levels of insulin can cause Sodium retention and sympathetic overactivity." (PMID 33644105, 2020). "Thus, accumulating evidence suggests that obesity-associated inflammation hinders the thermogenic and insulin sensitizing effects of both BAT and beige adipocytes." (PMID 32158768, 2020). "After years of obesity-associated hyperinsulinemia, the insulin secretory function in the pancreas could falter and eventually lead to hyperglycemia." (PMID 32899357, 2020). "Notably, the exosomal miR-26a level was negatively associated with BMI, HOMA-IR, fasting blood glucose, and other obesity/T2D features, suggesting a strong association of exosomal miR-26a with insulin sensitivity." (PMID 32092075, 2020). "The suggested mechanism is that obesity-related insulin deregulation and the adipokine-associated inflammatory response may activate proliferation." (PMID 32481621, 2020). "We aimed to test the hypothesis that FA composition of red blood cell total phospholipids (RBC-TPL) and SAT is associated with body fat centralisation (VAT/SAT ratio) and insulin sensitivity (SI) in black South African women with obesity." (PMID 32486525, 2020).
Obesity (continued). "More specifically, the target genes of miRNAs associated with the four bacterial species related to obesity participate in the fatty acid degradation, mineral absorption, carbohydrate digestion and absorption, insulin signaling pathway and glycerolipid metabolism." (PMID 33327530, 2020). "Thus, we elected to use this animal model to study mitochondrial fuel competition in insulin resistant skeletal muscle that lacks obesity-associated nutrient oversupply." (PMID 32612543, 2020). "Moreover, the same group also found circulating lactoferrin to be negatively associated with hyperglycemia, inflammatory markers and obesity, and directly associated with insulin sensitivity." (PMID 32752277, 2020). "Obesity is inversely associated with mitochondrial replication and skeletal muscle function, which are caused by cellular oxidative stress, lipotoxicity, and insulin resistance." (PMID 32411005, 2020). "Furthermore, GHS-R1α antagonists, GOAT inhibitors and the genetic deletion of GHS-R1α enhanced the release of insulin, glucose tolerance, insulin sensitivity and weight loss in in vivo models of obesity." (PMID 33381011, 2020). "Similarly, chronic consumption of alcohol was observed to be independently and inversely associated with resistance to insulin after adjusting for age, obesity, hypertension, fasting hyperglycemia, habit of drinking sweet beverages, and physical activity." (PMID 32283773, 2020). "We demonstrated that chronic consumption of alcohol was independently and inversely associated with fatty liver and resistance to insulin after adjusting for obesity, hypertension, fasting hyperglycemia, habit of drinking sweet beverages, physical activity, and age." (PMID 32283773, 2020). "Conversely, insulin signaling inhibits foxO activity by phosphorylation and 20E by controlling the expression of the gene encoding the transcriptional co-activator, “Diabetes and Obesity Regulated (DOR)” during feeding." (PMID 32457651, 2020). "Similarly, inactivation of the sensory receptor TRPV1, which functions upstream of CGRP in nociceptive sensory neurons, is associated with increased insulin secretion and resistance to diet-induced obesity." (PMID 33604590, 2020). "Obesity and elevation of the inflammatory response might have attenuated insulin signaling and have been associated with hyperglycemia in women with GDM." (PMID 32500037, 2020). "The reason(s) for such a disparity is/are unclear, but might involve the degree to which lipolytic activity and/or insulin action is reduced in association with obesity." (PMID 32120832, 2020). "Therefore, certain foods associated with excessive inflammation are also associated with insulin-stimulating foods, fat storage, and obesity." (PMID 32604970, 2020). "For example, obesity–insulin connections have been considered as potential risk factors for postmenopausal breast cancer, and the association between insulin resistances (IR) genotypes and phenotypes can be modified by obesity-lifestyle factors, affecting breast cancer risk." (PMID 32592352, 2020). "Interestingly, Sgms2 deficiency in mice increases insulin sensitivity and ameliorates high-fat diet-induced obesity and Hadh−/− mice, while having a disrupted β-oxidation pathway, are also protected from diet-induced obesity." (PMID 33143653, 2020). "Furthermore, increased Bifidobacteria and Lactobacilli, which are linked to decreased diet-induced obesity and improved insulin sensitivity have been further supported by soy-protein consumption." (PMID 32751533, 2020). "The findings presented here suggest that while IL‐6 produced by adipose tissue is associated with obesity, systemic levels of IL‐6 may be associated with weight loss and improved insulin sensitivity early after VSG‐induced weight loss." (PMID 32313680, 2020).